SNORD14C (small nucleolar RNA, C/D box 14C)
Gene: Small nucleolar RNA gene on chromosome 11 (123,059,335 to 123,059,422, reverse strand). Ensembl gene ENSG00000202252.
Gene Ontology:
Biological process: RNA processing
Cellular component: nucleolus
Homologues: Orthologues: chimpanzee SNORD14 (100% identical), macaque SNORD14 (100% identical), pig SNORD14 (93% identical), dog SNORD14 (90% identical), mouse Snord14c (77% identical), rat SNORD14 (77% identical), tropical clawed frog SNORD14 (77% identical), guinea pig SNORD14C (75% identical). Paralogues in human: SNORD14D (78% identical), SNORD14A (76% identical), SNORD14B (75% identical), SNORD14 (68% identical), SNORD14E (65% identical).
Diseases named in the same sentence as SNORD14C in open-access papers:
SNORD14C is named in the same sentence as 1 disease in open-access papers, as found by Europe PMC text mining. Sharing a sentence is not in itself a finding about the gene and the disease. The quoted sentences say what the papers report.
melanoma (1 paper, 2015). A malignant, usually aggressive tumor composed of atypical, neoplastic melanocytes. "The role of snord14c in melanoma progression is unknown, as snord14c is a member of the small nucleolar RNAs (snoRNAs) and is classified as a C/D box snoRNA that generally are linked to methylation." (PMID 26714172, 2015).